MATR3 (matrin 3)
Diseases named in the same sentence as MATR3 in open-access papers (continued):
Sharing a sentence is not in itself a finding about the gene and the disease.
breast carcinoma (8 papers, 2020 to 2024). "Surprisingly, MATR3 expression was significantly lower in the aggressive and metastatic breast cancer subtypes and higher expression levels were associated with better breast cancer patient survival, which suggests MATR3’s role as a prognostic biomarker." (PMID 32977861, 2020). "Although genomic deletions or mutations could affect MATR3 gene expression, such alterations are relatively rare in breast cancer according to the mutation analysis (1% or lower, cbioportal.org)." (PMID 32977861, 2020). "Moreover, high expression levels of MATR3 were associated with a good prognosis of breast cancer patients." (PMID 32977861, 2020). "An example of a pair with strong correlation is the lncRNA MALAT1, a key regulator in breast cancer, and the mRNA MATR3, an RNA-binding protein with tumor suppressive function in breast cancer." (PMID 38838009, 2024). "In the present study, we aimed to investigate the role of MATR3 in breast cancer, especially in BLBC." (PMID 32977861, 2020). "MATR3 expression was inversely correlated with the aggressive and metastatic nature of breast cancer." (PMID 32977861, 2020). "Taken together, flow cytometric analyses, PARP cleavage and the TAP-MS demonstrate that MATR3 promotes and its depletion suppresses apoptotic cell death in basal-like breast cancer cells potentially by interacting with apoptosis-controlling proteins." (PMID 32977861, 2020). "We also scrutinized MATR3 expression levels in the different subtypes of human breast cancer and the correlation between MATR3 expression and patient survival by bioinformatic analyses of publicly available transcriptome datasets." (PMID 32977861, 2020). "PARP cleavage upon Staurosporine confirms that MATR3 further promotes and its depletion suppresses apoptotic cell death in basal-like breast cancer cells." (PMID 32977861, 2020). "In the present study, we demonstrated the potential tumor-suppressive functions of MATR3 in basal-like breast cancer (BLBC)." (PMID 32977861, 2020). "We conducted bioinformatic analyses to examine the correlation between MATR3 expression and the aggressive phenotype of breast cancer subtypes." (PMID 32977861, 2020). "Here, we demonstrated that MATR3 suppresses tumorigenecity, induces apoptotic cell death, and inhibits migration and invasion of the basal-like breast cancer cells." (PMID 32977861, 2020). "Our data strongly suggest that MATR3 also offers the possibility to predict aggressiveness and metastatic potential of the given breast cancer and patient survival as a novel cancer prognostic biomarker." (PMID 32977861, 2020). "Moreover, low expression levels of MATR3 were related to unfavorable outcomes in breast cancer patients." (PMID 36830863, 2023). "Among several tumors, overexpression of MATR3 has been associated with hepatocellular carcinoma (HCC) and non-small cell lung cancer (NSCLC) stageI/II development and has tumor-suppressive activity in basal-like breast cancer." (PMID 37019990, 2023). "MATR3 was a highly conserved nuclear matrix protein, which was widely expressed in various tissues and involved in breast cancer-related biological processes, such as transcription, translation, RNA processing, DNA replication, apoptosis, and chromatin remodeling." (PMID 32802855, 2020). "Also, MATR3 potentially plays a role as a biomarker in predicting chemotherapy-sensitivity and patient survival in breast cancer patients." (PMID 32977861, 2020). "Therefore, we treated Staurosporine to two basal-like breast cancer cell lines and examined whether MATR3 further controls apoptosis by affecting PARP cleavage." (PMID 32977861, 2020). "In comparison to the normal samples (M0), AS switches occurring in patients with breast cancer metastasis (M1) were significantly different in COMMD4_AS2, MARK3, and MATR3." (PMID 36725888, 2023).
breast carcinoma (continued). "In this study, we found a higher PSI value in breast cancer patients than in normal samples for COMMD4_AS2, GNAS, MATR3, RHOC and COMMD4_AS1, whereas the PSI value was lower for MARK3, POLDIP3 and FASTK." (PMID 36725888, 2023). "We found that METTL3 depletion promoted exon inclusion of the alternative exons of GNAS, MATR3, POLDIP3 and promoted skipping of the alternative exons of COMMD4, MARK3 and the non-m6A modified transcripts FASTK and EXOC7 in both breast cancer cell lines." (PMID 36725888, 2023). "To compare the relative MATR3 expression levels in a small panel of human breast cancer cell lines with basal-like/triple-negative breast cancer (BLBC/TNBC) properties, we performed western blotting with a specific antibody against MATR3." (PMID 32977861, 2020). "Although we found variabilities along the stages, which reflects the heterogeneity of this disease, COMMD4_AS2, MARK3, MATR3, POLDIP3, COMMD4_AS1, and GNAS underwent AS switches in almost all stages of breast cancer, while RHOC displayed significant AS switches during stage IIB." (PMID 36725888, 2023). "RNA-sequencing dataset analysis demonstrated that MATR3 expression was significantly lower in the TNBC & BLBC compared to the other subtypes, which implies that MATR3 expression is inversely correlated with aggressive and metastatic nature of breast cancer." (PMID 32977861, 2020). "We observed that the AS events for COMMD4_AS2, GNAS, MATR3,COMMD4_AS1 and RHOC displayed a significant higher PSI value in cancer patients than in normal samples, while the PSI values were significantly lower for MARK3, POLDIP3 and FASTK in patients with breast cancer." (PMID 36725888, 2023). "In addition, the ChIP followed by qPCR assays was subsequently performed in Flag-MATR3 transfected breast cancer cells with or without MIDEAS-AS1 overexpression to determine the effect of MIDEAS-AS1 on MATR3 recruitment to the NCALD promoter." (PMID 37770991, 2023). "To examine whether MATR3 expression is correlated with the aggressiveness and poor prognosis of breast cancer, we compared its expression between triple-negative breast cancer (TNBC) and BLBC and other breast cancer subtypes." (PMID 32977861, 2020).
frontotemporal dementia (8 papers, 2018 to 2023). Frontotemporal dementia (FTD) comprises a group of neurodegenerative disorders, characterized by progressive changes in behavior, executive dysfunction and language impairment, as a result of degeneration of the medial prefrontal and frontoinsular cortices. "Several neurodegenerative diseases, including ALS and frontotemporal dementia, have been associated with MATR3 mutations." (PMID 37098514, 2023). "A more recent report reclassified a subset of patients with this diagnosis as having ALS and noted several additional MATR3 mutations in individuals with ALS and frontotemporal dementia (FTD), placing MATR3 in a family of genes implicated in familial ALS, FTD, and myopathy." (PMID 30015619, 2018). "Thus, MATR3 is among the family of genes including VCP, HNRNPA1, HNRNPA2B1 and SQSTM1 that cause “multisystem proteinopathy” associated with either one or a combination of ALS/frontotemporal dementia (FTD), VCPDM and Paget’s disease of bone." (PMID 32811564, 2020).
neuroblastoma (7 papers, 2018 to 2026). Neuroblastoma (NB) is the most common solid, extracranial childhood tumor. "The authors of the cited study showed that high expression of MATR3 is associated with poor event-free survival and OS of patients with neuroblastoma from the RNA-seq cohort." (PMID 36830863, 2023). "SNHG1 has also been shown to interact with the RNA-binding matrix protein, matrin-3 (MATR3) in neuroblastoma, and PP2A-c in bladder cancer." (PMID 37464317, 2023). "Coincidentally, the highest SNHG1 binding protein score in neuroblastoma also includes YBX1 (and also HnRNPL and MATR3), where the role of HnRNPL interacting with SNHG1 in PCa has been demonstrated." (PMID 41507135, 2026). "SNHG1 is reported to bind to certain RBPs like heterogeneous nuclear ribonucleoprotein L (HNRNPL) and matrin 3 (MATR3) and to promote the progression of prostate cancer (PCa) as well as neuroblastoma." (PMID 40510136, 2025).
dementia (6 papers, 2016 to 2025). Loss of intellectual abilities interfering with an individual's social and occupational functions. "The degree of dementia also appears to vary considerably in individuals with disease-associated MATR3 mutations." (PMID 33427209, 2021). "MATR3 is one of the newly identified dementia-causing genes." (PMID 34899276, 2021). "The pathogenic classified variant chr5:139307759:T:G in MATR3 (p.Phe115Cys) was identified via exome sequencing in a European family with ALS and dementia and segregated with disease." (PMID 41256702, 2025). "The initial study linking MATR3 mutations to ALS identified a Phe115Cys mutation in a patient with cognitive deficits, though this was reported only as dementia without detailed characterization." (PMID 33427209, 2021).
familial amyotrophic lateral sclerosis (4 papers, 2018 to 2023). An instance of amyotrophic lateral sclerosis that is caused by an inherited modification of the individual's genome. "Mutations in MATR3 have also been linked to familial amyotrophic lateral sclerosis, adding to a list of mutations in many proteins that function in RNA processing associated with this disease." (PMID 30425153, 2018). "Previous studies proved that mutations in MATR3 cause hereditary amyotrophic lateral sclerosis." (PMID 36952494, 2023).
malignant melanoma (4 papers, 2022 to 2024). "There was also upregulation of Matrin-3, a downstream component of the FGF2 pathway that mediates melanoma cell proliferation and survival, and BUB3, a mitotic checkpoint regulator." (PMID 39272836, 2024).
hepatocellular carcinoma (3 papers, 2021 to 2024). A malignant tumor that arises from hepatocytes. "Elevated levels of MATR3 are associated with lower overall survival, advanced clinical stage, and/or higher tumor grade in patients with neuroblastoma or hepatocellular carcinoma (HCC)." (PMID 38891112, 2024). "Of note, an early study of MATR3 localization has also described a population of MATR3 that is detectable in the cytoplasmic, microsomal, and polysomal fractions of rat liver and Ac2F hepatoma cells." (PMID 38891112, 2024). "Abnormal intron retention, as observed in hepatocellular carcinoma, also results in increased MATR3 mRNA abundance, further supporting the effects of alternative splicing on MATR3 transcript stability while implicating additional, as yet unknown mechanisms in MATR3 regulation at the RNA level." (PMID 33427209, 2021).
HIV-1 infection (3 papers, 2015 to 2025). The type species of lentivirus and the etiologic agent of acquired immunodeficiency syndrome (AIDS). "In this work we provide evidence of a critical role for MATR3 in acute HIV-1 infection and reactivation from latency." (PMID 30425153, 2018). "Here we demonstrate that Matrin 3 interacts with key proteins of the ZAP-degradation complex, and suppression of Matrin 3 drastically improves ZAPs ability to block HIV-1 infection, with similar findings for MoMuLV." (PMID 26129669, 2015). "In HIV-1 infection, Matrin 3 serves as a Rev cofactor important for the cytoplasmic accumulation of HIV-1 transcripts." (PMID 26129669, 2015). "During HIV-1 infection, it was demonstrated that Matrin 3 binds HIV-1 RNAs and acts as a Rev cofactor, promoting the accumulation of Rev-dependent unspliced and singly-spliced HIV-1 RNAs in the cytoplasm." (PMID 26129669, 2015). "In HIV-1 infection, Matrin 3 was shown to act as a Rev cofactor and promotes the accumulation of HIV-1 unspliced and singly-spliced transcripts in the cytoplasm." (PMID 26129669, 2015). "Therefore, in this work we wished to establish the role of MATR3 in acute HIV-1 infection of CD4+ T lymphocytes and in reactivation from latency following LRA treatment in HIV+ aviremic patients’ cells." (PMID 30425153, 2018). "Perhaps the best-studied role for MATR3 in a virus life cycle is during HIV-1 infection." (PMID 30425153, 2018). "Next, we went on to explore the Rev dependence by determining how MATR3 and MTR4 interact with HIV-1 RNA in a more physiological model of HIV-1 infection." (PMID 40021667, 2025). "Removal of Matrin 3 augments and broadens ZAP’s ability to inhibit HIV-1 infection—exposes the RNAs to attack by ZAP—and in effect leads to a more potent retroviral restriction factor." (PMID 26129669, 2015).
liposarcoma (3 papers, 2022 to 2023). A usually painless malignant tumor that arises from adipose tissue. "ALS models are commonly based on mutant superoxide dismutase 1 (SOD1), TAR DNA-binding protein 43 (TDP-43), fused in sarcoma or translocated in liposarcoma (FUS), the chromosome 9 open reading frame 72 (C9orf72) gene, ubiquilin 2 (UBQLN2), matrin 3 (MATR3), and senataxin (SETX)." (PMID 36672187, 2023).
muscular disease (3 papers, 2020 to 2025). Myopathy is a peripheral nervous system disease consisting of any abnormal condition or disease of the muscular tissues; commonly designates a disorder involving skeletal muscle. "Focusing on Matr3-a gene linked to muscle disorders-we demonstrate that its APA-miRNA regulatory balance is critical for efficient SC differentiation in vitro." (PMID 41429958, 2025). "Thus, we propose that the loss of Matr3 destabilizes chromatin loops at conserved hotspots related to muscular disease, and loop rearrangements contribute to changes in transcription factor occupancy and gene expression, leading to defects in development." (PMID 38341433, 2024). "Mutations in MATR3 have been first associated with muscular diseases." (PMID 32292882, 2020).
oral squamous cell carcinoma (3 papers, 2020 to 2023). "In the oral squamous cell carcinoma and normal endothelial cells, however, silencing MATR3 using siRNA promoted cell death, which indicates that the pro-apoptotic function of MATR3 may be cell-context dependent." (PMID 32977861, 2020).
sarcoma (3 papers, 2023 to 2025). A usually aggressive malignant neoplasm of the soft tissue or bone. "Among the genes mutated in ALS, however, several—including those for TDP-43 (TAR DNA-binding protein–43), MATR3 (matrin 3), FUS (fused in sarcoma), and hnRNPA1 (heterogeneous nuclear ribonucleoprotein A1)—encode RNA-binding proteins (RBPs) that share an important role in RNA metabolism." (PMID 40707625, 2025).
Alzheimer disease (2 papers, 2021 to 2022). A progressive, neurodegenerative disease characterized by loss of function and death of nerve cells in several areas of the brain leading to loss of cognitive function such as memory and language. "Cytoplasmic MATR3 was recently detected in subiculum from patients with Alzheimer disease (AD) but not age-matched controls." (PMID 33427209, 2021).
colorectal cancer (2 papers, 2017 to 2024). A primary or metastatic malignant neoplasm that affects the colon or rectum. "Similarly, knockdown of MATR3 decreased cell proliferation and/or increased apoptosis in oral squamous cell carcinoma cells, malignant melanoma cells, and colorectal cancer cells." (PMID 38891112, 2024). "Lastly, a recent study has demonstrated that MATR3 regulates mitotic spindle dynamics and cell proliferation by controlling the alternative splicing of CDC14B in colorectal cancer cells." (PMID 38891112, 2024).
motor neuron disease (2 papers, 2018 to 2021). "MATR3-related pathology, encompassing myopathy and motor neuron disease, represents an illustrative example of multisystem proteinopathy (MSP), such as other diseases associated to mutations in VCP, HNRNPA2B1, HNRNPA1, and SQSTM1 genes." (PMID 34659085, 2021). "Furthermore, the protein products for several genes that have been causally linked to ALS are found within the M2 module, including HNRNPA1, MATR3, and PFN1 and TDP‐43 itself, whereas HSPB1 (in M6) has been linked to hereditary motor neuropathy, a form of motor neuron disease." (PMID 29191947, 2018).
muscular dystrophy (2 papers, 2023 to 2024). Muscular dystrophy (MD) refers to a group of more than 30 genetic diseases characterized by progressive weakness and degeneration of the skeletal muscles that control movement. "For example, upon Matr3 depletion we observed rearrangement within the Ltbp4-Tgfb1 locus, a region linked to muscular dystrophy in GWAS42–44." (PMID 38341433, 2024).
non-small cell lung carcinoma (2 papers, 2023). A group of at least three distinct histological types of lung cancer, including non-small cell squamous cell carcinoma, adenocarcinoma, and large cell carcinoma. "Likewise, our previous report revealed that low MATR3 protein expression was an independent poor prognostic factor in non-small cell lung cancer." (PMID 36830863, 2023).
acute leukemia (1 paper, 2025). A clonal (malignant) hematopoietic disorder with an acute onset, affecting the bone marrow and the peripheral blood. "MATR3, a nuclear matrix protein that is thought to stabilize certain messenger RNA types, has also been shown to participate in creating the KMT2A-MATR3 fusion and accelerating the onset of acute leukemia." (PMID 40426895, 2025).
acute lymphoblastic leukemia (1 paper, 2023). Leukemia with an acute onset, characterized by the presence of lymphoblasts in the bone marrow and the peripheral blood. "Previously, the LINC00856 lncRNA was found to be involved in the response to acute lymphoblastic leukemia, and the down-regulation of MATR3 correlated with decreased levels of this lncRNA in MPS cells." (PMID 36833198, 2023).
acute myeloid leukemia (1 paper, 2021). Acute myeloid leukemia (AML) is a group of neoplasms arising from precursor cells committed to the myeloid cell-line differentiation. "In addition, affinity purification of the cohesin complex with Smc1a antibody in human acute myeloid leukemia (AML) cells, followed by mass spectrometry, identified Matr3." (PMID 34716321, 2021).
atherosclerosis (1 paper, 2025). A disease characterized by the build-up of fatty material and calcium deposition in the arterial wall resulting in partial or complete occlusion of the arterial lumen. "While endothelial cell and smooth muscle cell dysfunction have essential function in the occurrence and development of atherosclerosis, indicating the potential regulatory role of MATR3 in atherosclerosis development." (PMID 40950552, 2025).
Blindness (1 paper, 2018). Blindness is the condition of lacking visual perception defined as a profound reduction in visual perception. "In the CD4 cells of our patients, we found that SPPL2B expression was common to both those with raised WCC and jaw claudication whilst MATR3 was associated with raised WCC and long-term monocular blindness." (PMID 30037347, 2018).
brain tumour (1 paper, 2023). "Alterations in RBP expression levels and function have been associated with neurological disorders (e.g. HNRNPA1, MATR3, TIA1, and TARDBP and brain tumour development (e.g. Musashi1, SERBP1, PTB and HuR." (PMID 37294214, 2023).
breast tumors (1 paper, 2020). "In The Cancer Genome Atlas (TCGA) datasets, we found that MATR3 expression was higher in the normal breast tissues than in the breast tumors." (PMID 32977861, 2020). "We first compared MATR3 expression between normal breast tissues and primary breast tumors." (PMID 32977861, 2020).
Clear Cell Renal Cell Carcinoma (1 paper, 2023). "Therefore, the present study aimed to examine the expression levels and prognostic significance of MATR3 in clear cell renal cell carcinoma (ccRCC) patients." (PMID 36830863, 2023).
cognitive deficits (1 paper, 2021). "Four missense mutations, including Ser85Cys, located in MATR3’s IDRs were associated with ALS with or without cognitive deficits." (PMID 33427209, 2021).
congenital myopathies (1 paper, 2024). "The role of SGs in skeletal muscle homeostasis has been explored in the setting of congenital myopathies such as Welander distal myopathy (WDM) and Matrin 3 myopathy." (PMID 39513903, 2024).